PLG (plasminogen)
Diseases named in the same sentence as PLG in open-access papers (continued):
Sharing a sentence is not in itself a finding about the gene and the disease.
periodontitis (11 papers, 2015 to 2024). An acute or chronic inflammatory process that affects the tissues that surround and support the teeth. "For example, neutrophil activation through fibrin-CD11b binding can mediate inflammatory bone loss in experimental periodontitis [74•]; these findings support individuals harboring congenital deficiency in plasminogen that develops periodontitis [74•]." (PMID 38418800, 2024). "In concordance with the sites of impaired wound healing in plasminogen-deficient humans, plasminogen-deficient mice develop periodontitis with detachment of gingival tissue that is characterized by fibrin deposition." (PMID 33567773, 2021). "Another study reported PLG variants associated with both chronic and aggressive periodontitis." (PMID 36589419, 2022). "Interestingly, genetic variants in the human plasminogen gene have not only been associated with atherosclerotic cardiovascular diseases, but were also associated with aggressive periodontitis in Northern European study populations." (PMID 29163477, 2017). "Further approaches to ligneous periodontitis with administrating the recombinant plasminogen to this patient was considered before the onset of Behçet's disease." (PMID 37940896, 2023). "There is evidence for plasminogen (PLG) as a shared genetic risk factor for coronary artery disease and periodontitis." (PMID 32489774, 2020). "In a study by Sulniute and coworkers, the role of plasminogen in periodontitis was investigated using a Plasminogen knockout mouse model." (PMID 29163477, 2017). "Below we summarize the observations in three different protease knockout mouse models, those with the following genes knocked out: Mmp-8, Cathepsin K, and plasminogen in periodontitis mouse models." (PMID 29163477, 2017). "Recent studies indicate that components of the plasminogen (Plg)/plasmin (Pm) system are expressed in tissues of the oral cavity, such as the salivary gland, and contribute to microbial infection and inflammation, such as periodontitis." (PMID 36766787, 2023). "There are indications that aberrant inflammatory reactivity, determined by genetic variants in the loci CDKN2B-AS1 (ANRIL), PLG, CAMTA1/VAMP3 and VAMP8 could partially explain the epidemiological link between periodontitis and cardiovascular diseases." (PMID 32489774, 2020). "Additionally, the involvement of bacterial factors that modulate the process of plasminogen activation and fibrinolysis during periodontitis is also described, providing a remarkable example of a dual use of this host system in the development of chronic diseases." (PMID 37445613, 2023).
lung carcinoma (9 papers, 2013 to 2025). "A set of genes involved in epithelial cell growth (ERBB2, EGF, and FGF2) and Plasminogen (PLG) were connected to Cancer and Lung cancer in the Year 2 SPP1 network." (PMID 37513116, 2023). "Subsequently, these genes co-overexpress in the negative regulation of plasminogen activation, a system that has dissimilar gene expression patterns among lung cancer subtypes." (PMID 36142846, 2022). "MMP-2 and -12 act on plasminogen to produce angiostatin, an anti-angiogenic component, which suppresses metastasis and tumor growth in lung cancer." (PMID 34912809, 2021). "The displacement of S100A10 from annexin A2 by DLC1, a Rho GTPase-activating protein (RhoGAP) that functions as a tumor suppressor, results in the attenuation of plasminogen activation and impaired invasion of A549 lung cancer cells." (PMID 30572596, 2018). "The displacement of S100A10 from annexin A2 attenuates plasminogen activation, impairing colony formation and growth of A549 lung cancer cells." (PMID 30572596, 2018). "The expressions of ENO1, uPA, uPAR and plasminogen on the surface of PE089 cells, a human lung cancer cell line, and the murine Lewis lung carcinoma cells transfected with the luciferase gene (LLC/luc) were examined and confirmed by FACS analysis." (PMID 23894455, 2013). "In this study, we demonstrated that surface ENO1 interacted with plasminogen, uPA and uPAR on the PE089 and LLC/luc lung cancer cell lines." (PMID 23894455, 2013).
pancreatic cancer (9 papers, 2014 to 2024). "The serine protease uPA catalyses the conversion of plasminogen to plasmin, and its receptor uPAR has been studied in pancreatic cancer cells." (PMID 34439122, 2021). "Similarly, S100A10 was found to function in surface plasminogen activation, invasiveness, and the growth of pancreatic cancer cells." (PMID 36114176, 2022). "uPA is an enzyme responsible for cleavage of plasminogen to plasmin which mediates the degradation of the extracellular matrix for cancer cell invasion and has been shown to contribute to the invasive behavior of pancreatic cancer." (PMID 29573228, 2018). "Here, we determine the role of plasminogen in PDAC tumor growth and metastasis using mouse and human xenograft models of pancreatic cancer." (PMID 37971174, 2024). "In our previous report, we demonstrated that ENO1 cell surface expression is important for plasminogen-dependent invasion, and that targeting of ENO1 with a monoclonal antibody inhibits the invasiveness of pancreatic cancer cells." (PMID 28086938, 2017). "In pancreatic cancer, ANXA2 is highly expressed, acts as a tPA receptor to activate plasminogen, and consequently increases the invasiveness of pancreatic cancer cells by altering the extracellular matrix." (PMID 24591759, 2014).
asthma (8 papers, 2009 to 2023). "This study found ICS weaning to increase the levels of plasminogen, thus highlighting that in untreated moderate asthma, increased risk of fibrinolysis is corrected by ICS." (PMID 37529042, 2023). "A weak inverse relationship was documented for TNFα and plasminogen in asthma (β = −0.1 [95% CI, −0.18 to −0.03]) and in the controls (β = −0.26 [95% CI, −0.38 to −0.15])." (PMID 28429138, 2017). "Furthermore, ovalbumin-induced pulmonary inflammation is strongly inhibited by genetic depletion of plasminogen via suppressing the downregulation of IL-5, tumour necrosis factor-α and gelatinases, which are mediators of asthma and collagen deposition." (PMID 30089611, 2018). "These include a rare p.Arg172Gly missense of plasminogen associated with higher platelet count, lower D-dimer concentration and lower platelet reactivity and a rare splice acceptor variant of IL33 associated with lower eosinophil count and lower risk of asthma and allergic rhinitis." (PMID 28787443, 2017). "In addition, using human plasminogen minimises the risk of an immune response to non-human proteins, which could cause severe asthma/anaphylactic reactions when inhaled." (PMID 37376068, 2023). "Interestingly, PLAU and PAI-1 expression are also elevated in sputum from asthma and COPD subjects suggesting the plasminogen system may be augmented in these diseases." (PMID 19878584, 2009).
colorectal cancer (8 papers, 1997 to 2025). A primary or metastatic malignant neoplasm that affects the colon or rectum. "RNA interference-mediated downregulation of S100A10 gene expression in colorectal cancer cells, has been shown to result in a complete loss in plasminogen-dependent cellular invasiveness." (PMID 18827820, 2008). "The finding that S100A10 was hypermethylated in medulloblastoma cell lines and tumours was unexpected, as its overexpression has previously been associated with plasminogen-dependent cellular invasiveness in fibrosarcoma and colorectal cancer cells." (PMID 17579622, 2007). "On the one hand, Ahsg triggers the secretion of ‘adhesion competent’ exosomes containing Ahsg, plasminogen, and histones, promoting colorectal cancer (CRC) cell adhesion and spreading." (PMID 39684629, 2024). "In addition, we have previously demonstrated that S100A10 colocalizes with uPA receptor (uPAR) at the cell surface of HT1080 fibrosarcoma and Colo222 colorectal cancer cells to drive plasminogen activation." (PMID 30009399, 2018). "The uPA-plasminogen system is also crucially important in angiogenesis, and plasmin in turn might activate meprin-α as a downstream angiogenic effector in colorectal cancer." (PMID 22096485, 2011). "In conclusion, these findings emphasize the relevance of the intestinal plasminogen activation system for survival prognosis of patients with colorectal cancer and, in the future, might constitute a patient selection criterion for adjuvant therapy." (PMID 9192984, 1997).
gastric cancer (8 papers, 2019 to 2025). A primary or metastatic malignant neoplasm involving the stomach. "This phenomenon may be relevant for the development of gastric pathologies, given the central role of uPAR in plasminogen-mediated extracellular matrix remodeling, vitronectin-dependent cell adhesion and migration, and its upregulation in gastric cancer and associated prognostic impact." (PMID 32660136, 2020). "In this work, we aim to identify key regulators of plasminogen activation associated with tumorigenesis and explore potential mechanisms in gastric cancer (GC)." (PMID 31218131, 2019). "Succinylation at K47 reduces S100A10 from its ubiquitination and proteasomal degradation and allows for plasminogen activation and gastric cancer cells to migrate and invade the gastric cancer cells." (PMID 40865948, 2025). "The data also suggests novel therapeutic directions such as blocking IL-6 signaling from myeloid cells and plasminogen activation in activated endothelial cells for treating gastric cancer." (PMID 36550535, 2022). "Furthermore, the combination of recombinant oncolytic adenoviruses containing plasminogen Kringle 5 mutant and MnSOD significantly inhibited gastric cancer growth." (PMID 40092690, 2025). "Additionally, SERPINE1 can indirectly enhances the migratory and invasive abilities of gastric cancer cells by inhibiting plasminogen activators, like tPA and uPA." (PMID 40182050, 2025). "Since plasminogen takes an active part in blood coagulation, we compared the concentrations of fibrinogen in the blood of patients with gastric cancer related to both positive and false-negative IgG-LysK coefficients." (PMID 39001286, 2024). "In addition, ENO1 promotes the plasminogen activation system and upregulates integrin to enhance the migration and invasion of cancers 46-48; ENO1 regulates gastric cancer cells stemness by stimulating glycolysis." (PMID 35844805, 2022).
influenza (8 papers, 2011 to 2025). An acute viral infection of the respiratory tract, occurring in isolated cases, in epidemics, or in pandemics; it is caused by serologically different strains of viruses (influenzaviruses) designated A, B, and C, has a 3-day incubation period, and usually lasts for 3 to 10 days. "Here, we report that a molecule of the fibrinolytic system, plasminogen, contributes to inflammation caused by influenza." (PMID 23555246, 2013). "Pre-existing bacteria, such as S. pneumoniae, can further exacerbate influenza severity by secreting proteases that activate HA or by stimulating host proteases such as plasminogen, enhancing viral replication and infectivity." (PMID 40005491, 2025). "For instance, plasmin, the active form of plasminogen, can cleave hemagglutinin into its active form, enabling influenza viral entry." (PMID 40377310, 2025). "Plasminogen (which opposes clot formation) appears to promote destructive inflammation during influenza infection." (PMID 31616667, 2019). "Since plasminogen is proven to play an important role in influenza pathogenesis further exploring the biology, activation and inhibition of plasminogen in influenza infection would be of great interest." (PMID 24884666, 2014). "Inhibiting the action of plasminogen protected mice from severe influenza infections, including those caused by H5N1 and H1N1 pandemic 2009 viruses and may be a promising novel strategy to treat influenza." (PMID 23555246, 2013).
ovarian carcinoma (8 papers, 2011 to 2025). A malignant neoplasm originating from the surface ovarian epithelium. "PLG has been found as a positive predictive biomarker for advanced ovarian cancer, and similar findings have recently been described in advanced ovarian cancer." (PMID 35655917, 2022). "Tetranectin binds to kringle 4 of plasminogen, enhancing the plasminogen activation by tissue-type plasminogen activator in the presence of poly-D-lysine Low serum levels of tetranectin (CLEC3B) are associated with increased risk of second-line chemoresistance in patients with ovarian cancer." (PMID 22091389, 2011). "Additionally, in order to test whether the compound truly works as a PAI-1 inhibitor of uPA, the enzymatic activity of uPA was assessed by casein-plasminogen zymography in three ovarian cancer cell lines, SKOV3ip1 (PAI-1 positive), HeyA8 (PAI-1 positive) and OVCAR3 (PAI-1 negative)." (PMID 29163796, 2017). "In ovarian cancer cell lines, cell migratory and invasive phenotype is reduced by active PAI-1 due to its ability to inhibit plasminogen activation compared to their plasminogen activator system profiles." (PMID 23988121, 2013).
prostate carcinoma (8 papers, 2006 to 2025). A carcinoma that arises from epithelial cells of the prostate gland. "We also identified an inverse association of PLG, a serine protease targeted by transexamic acids and several classes of thrombolytics, with prostate cancer risk overall and with early onset disease." (PMID 38878676, 2024). "One exemplar protein of this metabolic pathway enrichment, enolase 1 (ENO1), converts 2-phosphoglycerate to phosphoenolpyruvate and serves as a cell surface receptor for plasminogen, where it is potentially involved in prostate cancer cell migration." (PMID 39125581, 2024). "One molecular study found that PLG is generated by the cancer-mediated proteolysis of plasminogen which is released by human prostate carcinoma cells." (PMID 38878676, 2024). "We previously demonstrated the increased binding of IgG to human plasminogen (PLG) in plasma of patients with prostate cancer (PC) compared to healthy controls." (PMID 34440049, 2021). "suPAR can be used as an effective molecular scavenger of uPA in human prostate cancer cells with high uPA-uPAR expression, and an increase in suPAR is related to plasminogen inhibition in patients with paroxysmal nocturnal hemoglobinuria." (PMID 34779798, 2021). "Moreover, adenocarcinomas such as prostate cancer have been reported to induce systemic fibrinolytic activity through tumor-derived proteolytic enzymes, which can activate plasminogen and degrade fibrinogen." (PMID 41002593, 2025). "In addition to the important role of these metalloproteinases, prostate cancer invasion is also highly dependent upon the activity of the urokinase proteinase system consisting of the serine protease urokinase, its cell surface receptor uPAR and inhibitors such as plasminogen activator inhibitors." (PMID 16756681, 2006). "Currently, several studies are investigating combination therapy including plasminogen activation or inhibition for treatment of several cancer types, though not specifically for prostate cancer, in phase I/II trials." (PMID 38878676, 2024).
coronary artery disease (7 papers, 2011 to 2024). "Tetranectin also enhances plasminogen activation and plasma TNA levels have been inversely associated with coronary artery disease." (PMID 26772976, 2016). "The rapid progression of coronary artery disease in patients with increased Lp(a) levels may be related to an interference with thrombolysis through the partial structural similarity of Lp(a) and plasminogen." (PMID 39685569, 2024).
depression (7 papers, 2012 to 2025). "Clearly, validating preclinical findings in human populations and investigating the clinical utility of modulating the plasminogen system for depression treatment are extremely important." (PMID 40725146, 2025). "Targeting the plasminogen system through biomarker discovery and the development of novel therapeutic interventions represents a significant and promising avenue for future research in depression." (PMID 40725146, 2025). "With the significant role of proBDNF in depression pathogenesis, tPA or other tPA/plasminogen cascade components such as PAI-1 could be important for depression pathogenesis or therapeutic mechanisms." (PMID 29348904, 2017). "The authors of this paper suggest that statins could be useful for patients with major depression with an abnormality in the tPA-plasminogen pathway or co-morbidities relating to cardiovascular disease." (PMID 23204984, 2012). "Studies on the neurotrophic factor hypothesis of depression indicate that the tissue‐type plasminogen activator (tPA) plasminogen system plays an important role in the pathophysiological process of depression by regulating the transformation of pro‐BDNF to mBDNF." (PMID 39639753, 2024). "This narrative review explores the intricate relationship between the plasminogen activator system (PAS), comprising urokinase-type plasminogen activator (uPA) and tissue-type plasminogen activator (tPA), and a range of neuropsychiatric disorders, including depression and anxiety." (PMID 40725146, 2025). "Therefore, the high levels of PAI-1 might inhibit the tPA/plasminogen system and inhibit cleavage of proBDNF, resulting in impaired BDNF signalling, which could result in reduced neural plasticity in the medial prefrontal cortex circuits in depression." (PMID 27456456, 2016).
nephrotic syndrome (7 papers, 2012 to 2024). A collection of symptoms that include severe edema, proteinuria, and hypoalbuminemia; it is indicative of renal dysfunction. "RVT predominantly occurs in patients with nephrotic syndrome, particularly in cases of membranous nephropathy, likely because of the loss of anticoagulant proteins (antithrombin and plasminogen) in the urine." (PMID 38921266, 2024). "Plasma and urinary levels of plasminogen and plasmin are elevated in patients with proteinuria and nephrotic syndrome." (PMID 26942026, 2016). "On the other hand, recent work from our group demonstrated that mice lacking urokinase-type plasminogen activator (Plau−/−) or plasminogen (Plg−/−) were not protected from ENaC activation and sodium retention in experimental nephrotic syndrome." (PMID 35312839, 2022).
viral infection (7 papers, 2010 to 2025). "As S. pneumoniae is able to bind plasminogen and host-derived activator onto its surface and transport both proteins to the site of viral infection, it can possibly facilitate and increase the cleavage of viral HA into its active form." (PMID 35632805, 2022). "Upon A/Netherlands/602/09 virus infection, release of cytokines in the BAL was also significantly higher in WT mice compared to PLG-KO mice at day 5 but not at day 2 post-inoculation." (PMID 23555246, 2013).
coagulopathy (6 papers, 2017 to 2025). "The impact of plasminogen on coagulation disorders in DM is further aggravated as plasminogen is also a pro-inflammatory factor, thereby promoting insulin resistance and exacerbating a pro-thrombotic state." (PMID 34072487, 2021). "Elapid venom proteases, such as snake venom serine proteases and disintegrin-like toxins, are known to inflict many coagulopathies, including the inhibition of platelet aggregation, and thrombin-, plasminogen-, and bradykinin-like effects." (PMID 34759827, 2021). "Biomarkers of coagulopathy and inflammation, platelet counts, FDP, PT, α2-PI, AT III, plasminogen, and C-reactive protein were significantly different between the two groups." (PMID 28841902, 2017).